SIRT3 (sirtuin 3)
Diseases named in the same sentence as SIRT3 in open-access papers (continued):
Sharing a sentence is not in itself a finding about the gene and the disease.
pancreatic cancer (continued). "In pancreatic cancer cells, the dysregulation of SIRT3 correlates with impaired CII activity, contributing to mitochondrial dysfunction and promoting tumor progression." (PMID 39682281, 2024). "SIRT3 expression is noticeably reduced in cells afflicted with hepatocellular and pancreatic cancers, while a rise in SIRT3 levels corresponds with a heightened chance of overall survival without relapse." (PMID 37175631, 2023). "SIRT3 overexpression is also involved in inhibiting pancreatic cancer cell growth by inhibiting iron-regulatory protein 1 (IRP1) enrichment, thereby suppressing transferrin receptor 1 (TfR1) and TfR1-mediated iron uptake and cell growth." (PMID 37175631, 2023). "Both SIRT3 and SIRT7 appear to function as tumour suppressors in the context of pancreatic cancer; low levels of both proteins were associated with more aggressive tumour phenotypes and poorer patient outcome." (PMID 26121130, 2015). "Patients with low levels of nuclear SIRT3 in their tumour were more likely to present with high grade, poorly differentiated pancreatic tumours (p = 0.015 and p = 0.05 respectively)." (PMID 26121130, 2015). "Our data suggest that Pfn1 is a tumor suppressor in pancreatic cancer that acts via a novel mechanism of regulating the SIRT3-HIF1α axis, independently of its cytoskeleton-related activity." (PMID 25103363, 2014). "In the present study, resveratrol inhibited the expression of SIRT1, SIRT2 and SIRT3 in pancreatic cancer cells, thus suggesting a role of SIRT1 as a tumor suppressor in cancer cells." (PMID 21980390, 2011). "Since Sirts regulate tumor formation and angiogenesis, we next examined the effects of resveratrol on the expression of Sirt1, Sirt2 and Sirt3 in pancreatic cancer cells by q-RT-PCR." (PMID 21980390, 2011). "Indeed, transfection experiments showed that overexpression of SIRT3 in pancreatic cancer cells (PANC1) significantly inhibited cell proliferation, whereas knockdown of SIRT3 by shRNA enhanced cell growth in vitro." (PMID 41391757, 2025). "As such, up-regulation of SIRT3 by abrogating RCC1 might by a potentially effective strategy to overcome resistance to this drug in pancreatic cancer." (PMID 41391757, 2025). "Interestingly, we found that the levels of SIRT3 expression significantly affected the sensitivity of pancreatic cancer cells to MRTX1133, a KRASG12D inhibitor in phase I/II clinical trial." (PMID 41391757, 2025). "In pancreatic cancer, patients with low SIRT3 expression seem to exhibit a rapid recurrence and short survival, while high SIRT3 expression could inhibit in vitro cell proliferation." (PMID 41391757, 2025). "Thus, targeting SIRT3 in pancreatic cancer represents a critical axis in regulating tumorigenesis, given its involvement in mitochondrial homeostasis, oxidative stress regulation and metabolic adaptation." (PMID 39682281, 2024). "Importantly, the acetylation of GOT2 at K159 is elevated in human pancreatic tumors and correlates with diminished SIRT3 expression." (PMID 39682281, 2024). "Importantly, SIRT3 acts as a tumor suppressor by attenuating TfR1 expression and iron uptake, thereby curbing the proliferative capacity of pancreatic cancer cells." (PMID 39682281, 2024).
pancreatic cancer (continued). "Moreover, SIRT3 assumes a critical role in modulating glycolysis in pancreatic cancer, particularly by counteracting the tumor-promoting consequences of dysregulated glycolytic activity." (PMID 39682281, 2024). "Furthermore, the expression of sirtuin 3 is negatively related to the expression of TFR1 in human pancreatic cancer." (PMID 29789480, 2018). "Interestingly, our study, utilising a human resected pancreatic tumour TMA, investigated all seven sirtuins and has implicated SIRT3 and SIRT7 as being associated with more advanced pancreatic cancer." (PMID 26121130, 2015). "In conclusion, we described a novel regulatory mechanism whereby pancreatic cancer proliferation is inhibited by the interaction of Pfn1 and SIRT3 to destabilize HIF1α, which results in reduced expression of HIF1α target genes that coordinate aerobic glucose consumption." (PMID 25103363, 2014). "Our study showed that overexpression of SIRT3 could significantly inhibit the proliferation of pancreatic cancer cells in vitro and suppress tumor growth in vivo, whereas suppression of SIRT3 expression by shRNA significantly promoted pancreatic cell proliferation in vitro and tumor growth in mice." (PMID 41391757, 2025). "The effect of SIRT3 on pancreatic cancer development largely remains unclear." (PMID 41391757, 2025). "Importantly, we found that induction of KRASG12D expression led to a significant decrease in SIRT3 expression, suggesting that down-regulation of SIRT3 by KRAS might be a mechanism that facilitates KRAS-driven pancreatic cancer development." (PMID 41391757, 2025). "Thus, it appeared that the down-regulation of SIRT3 expression by KRASG12D might be a mechanism by which pancreatic cancer cells become resistance to the KRASG12D inhibitor." (PMID 41391757, 2025). "Since conflicting/opposite impacts of SIRT3 on tumor growth have been reported in the literature, we thus performed patient survival analysis as well as in vitro and in vivo experiments to evaluate the role of SIRT3 on pancreatic cancer development in the context of KRAS activation." (PMID 41391757, 2025). "Thus, SIRT3 may act as a tumor suppressor in pancreatic cancer, and GOT2 deacetylation drugs targeting this need to be explored." (PMID 40247913, 2025). "Kaplan–Meier survival analysis further corroborated these findings, demonstrating a significant association between negative SIRT3 expression and poorer overall prognosis, thereby underscoring SIRT3’s potential as a critical biomarker in pancreatic cancer prognosis." (PMID 39682281, 2024). "By restoring SIRT3 expression, it is possible to modulate mitochondrial function, induce apoptosis and disrupt hypoxia-driven oncogenic survival mechanisms, positioning SIRT3 as both a potent tumor suppressor and a critical biomarker for pancreatic cancer prognosis." (PMID 39682281, 2024). "SIRT3 has been identified as the main deacetylase of GOT2, and its deacetylation may not affect the enzyme activity of GOT2 itself but impairs the GOT2-MDH2 association, which negatively regulates malate-aspartate shuttle and impairs pancreatic cancer cell proliferation." (PMID 40247913, 2025). "Overexpression of SIRT3 significantly enhanced the cytotoxicity of MRTX1133 against pancreatic cancer cells (PANC1) in a colony formation assay, whereas SIRT3 knockdown by shRNA reduced the sensitivity of PANC1 cells to MRTX1133 treatment." (PMID 41391757, 2025). "Analysis of pancreatic cancer patient survival data in the TCGA database revealed that patients with high SIRT3 expression exhibited better overall survival compared to those with lower low SIRT3 expression, suggesting that SIRT3 might have suppressive effect on pancreatic cancer." (PMID 41391757, 2025). "Since knockout of SIRT5 has been reported to promote the KRASG12D-driven PDAC progression in the KPC mouse model, we mainly focused our study on the regulation of SIRT3 by KRASG12D and its potential role in KRAS-driven pancreatic cancer development." (PMID 41391757, 2025).
pancreatic cancer (continued). "Considering our new finding that KRAS down-regulated SIRT3 through the guanine exchange factor RCC1 in vitro, we thus further evaluated the role of RCC1 in affecting pancreatic cancer cell proliferation and tumor growth in vivo." (PMID 41391757, 2025). "elucidated a novel mechanism whereby SIRT3‐dependent GOT2 acetylation affects the malate–aspartate NADH shuttle activity and promotes pancreatic tumor growth." (PMID 30714292, 2019). "The overexpression of sirtuin 3 decreases TFR1 expression by repressing the IRP1 and inhibits pancreatic cancer cells proliferation, and iron and TFR1 expression are higher in the sirtuin 3 null mice pancreas." (PMID 29789480, 2018). "Our data suggests that SIRT3 and SIRT7 possess tumour suppressor properties in the context of pancreatic cancer." (PMID 26121130, 2015). "A knockdown of RCC1 in PANC-1 cells could significantly upregulate SIRT3 expression and inhibited cancer cell proliferation in vitro and tumor growth in vivo, indicating a critical role of RCC1 in pancreatic cancer development." (PMID 41391757, 2025). "In addition, SIRT3 (sirtuin-3)-dependent GOT2 acetylation stimulates the malate-aspartate NADH shuttle activity and oxidative protection, thereby promoting pancreatic tumor growth." (PMID 40247913, 2025). "By modulating SIRT3 expression, ZEB1 not only drives aerobic glycolysis but also contributes to the broader metabolic flexibility and survival of pancreatic cancer cells under the hypoxic and nutrient-poor conditions leading to alterations in the tumor microenvironment." (PMID 39682281, 2024). "Immunohistochemical analyses across 79 pancreatic cancer patients revealed a pronounced downregulation of SIRT3 in cancer tissues relative to adjacent non-cancerous tissues, with statistical significance (p < 0.001)." (PMID 39682281, 2024). "Additionally, miR-421 directly represses SIRT3, leading to altered HIF-1α expression through the modulation of histone acetylation at H3K9, in pancreatic cancer." (PMID 39682281, 2024). "However, pharmacological agents like chrysin nanoparticles (CCNPs), which restore CII activity and SIRT3 expression, have demonstrated significant potential in reactivating ETC function, thereby inducing apoptosis and reducing the viability of pancreatic cancer cells." (PMID 39682281, 2024). "Additionally, SIRT3 impedes the malate-aspartate shuttle by deacetylating glutamate oxaloacetate transaminase 2 (GOT2), curtailing glycolysis and thus inhibiting the growth of pancreatic tumor cells." (PMID 38773972, 2024). "As a restriction enzyme that regulates the glycolysis process, GOT2 is deacetylated by SIRT3, thus obstructing the transport of cytosolic nicotinamide adenine dinucleotide hydrogen (NADH) into the mitochondria to achieve the purpose of blocking the growth of pancreatic tumors." (PMID 35832551, 2022). "Besides, SIRT3 inhibits the aggregation of iron regulatory protein 1 (IRP1), and further reduces the transferrin receptor (TfR1) expression, thus, regulating cellular iron metabolism to affect the proliferation of pancreatic cancer cells." (PMID 35832551, 2022). "In this study, we validated Pfn1 as a tumor-suppressor in pancreatic cancer, and identified a novel mechanism of PFN1 regulation of the SIRT3- HIF1α axis, independent of its cytoskeleton-related activity." (PMID 25103363, 2014).
pulmonary arterial hypertension (16 papers, 2015 to 2024). Pulmonary arterial hypertension (PAH) is a group of diseases characterized by mean pulmonary artery pressure >20 mmHg and elevated pulmonary arterial resistance leading to right heart failure. "For example, the lungs of patients with PAH have reduced expression of mitochondrial deacetylase SIRT3 and SIRT3 deficiency in mice promotes pulmonary hypertension in a mechanism that involves inhibition of PDH function." (PMID 35269553, 2022). "In this study, Shufeiya Recipe was used as an intervention in MCT-induced pulmonary hypertension in rats to observe its effect in improving PH and regulating SIRT3/FOXO3a and its downstream PI3K/AKT/eNOS and Ras/ERK signaling pathways." (PMID 35222742, 2022). "The impact of the Shufeiya Recipe on oxidative stress damage in rats with pulmonary hypertension and the regulation of SIRT3/FOXO3a and its downstream signaling pathways were determined." (PMID 35222742, 2022). "In summary, our results indicate that Shufeiya Recipe can improve MCT-induced pulmonary hypertension in rats by regulating SIRT3/FOXO3a and its downstream PI3K/AKT/eNOS and Ras/ERK signaling pathways." (PMID 35222742, 2022). "Furthermore, Sirt3 deficiency in mice has been associated with development of pulmonary arterial hypertension (PAH), which causes right ventricular hypertrophy." (PMID 29497772, 2018). "Moreover, it prevents pulmonary arterial hypertension (PAH) by increasing Sirt3 expression, deacetylating cyclophilinD, and preventing mPTP opening in a monocrotaline (MC)-treated rat model." (PMID 36675125, 2023). "Another deacetylase, SIRT3, also contributes to the pathogenesis of pulmonary hypertension." (PMID 37153765, 2023). "Also, a reduction of the mitochondria-localized deacetylase sirtuin 3 gene (SIRT3) expression suppresses mitochondrial function, inhibits apoptosis, and activates several pulmonary hypertension-related transcription factors." (PMID 31771195, 2019). "Indeed, mice lacking SIRT3 develop spontaneous pulmonary arterial hypertension." (PMID 37153765, 2023). "Also, in mice lacking sirtuin 3 (a mitochondrial deacetylase), mitochondrial acetylation is increased and many mitochondrial enzymes and complexes are inhibited, thus inhibiting mitochondrial function and leading to the emergence of spontaneous pulmonary arterial hypertension (PAH)." (PMID 35321239, 2022).
chronic kidney disease (15 papers, 2018 to 2026). Impairment of the renal function secondary to chronic kidney damage persisting for three or more months. "Researchers have reported that both Sirt3 and Sirt6 are involved in vascular calcification caused by chronic kidney disease and aging." (PMID 40523615, 2025). "Furthermore, the emergence of endothelial-to-mesenchymal transition in the kidney (which promotes fibrosis in chronic kidney disease) is a consequence of a SIRT3 deficiency." (PMID 39000044, 2024). "Cluster 2 captured the metabolic decline, with loss of Cystathionine beta‐synthase (CBS), a critical enzyme in sulfur amino acid metabolism and linked to oxidative stress and chronic kidney disease (CKD), and Sirt3, a regulator of mitochondrial ROS through Superoxide dismutase (SOD2)." (PMID 41508419, 2026). "Sirt3 is highly expressed in renal tissues and has been widely studied for its role in acute and chronic kidney diseases." (PMID 31929854, 2019). "Additionally, elevated UCP1 levels have been reported to reduce oxidative stress by stabilizing SIRT3, ultimately alleviating renal interstitial fibrosis in chronic kidney disease." (PMID 40120980, 2025). "Therefore, modulation of SIRT3 activity in diseased kidneys might be a novel therapeutic mechanism for the treatment of acute or chronic kidney disease." (PMID 31936371, 2020).
melanoma (15 papers, 2017 to 2025). A malignant, usually aggressive tumor composed of atypical, neoplastic melanocytes. "Overall, these are important observations to demonstrate a crucial connection between SIRT3 and key cancer/melanoma-associated signaling events." (PMID 33937086, 2021). "For example, the amplification of mitochondria via the induction of SIRT3 would selectively target aggressive melanomas with the loss of mitochondrial SOD2 mitochondria and induce cell death via ROS." (PMID 34831420, 2021). "The goal of this study was to validate the pro-proliferative function of SIRT3 in melanoma and establish its associated potential mechanisms, especially focusing on metabolic regulation." (PMID 33937086, 2021). "Further, IPA gene network analysis of SIRT3 modulated genes revealed the interactions among these genes in addition to several melanoma-associated genes." (PMID 33937086, 2021). "As SIRT3 has been implicated in regulating cellular metabolism, we determined the role of SIRT3 in metabolic regulation of melanoma cells." (PMID 33937086, 2021). "IPA exploration of the gene network indicated the connection of SIRT3 modulated genes along with several melanoma-associated genes (MYC, PI3K, AKT, CD3, ERK, and AMPK)." (PMID 33937086, 2021). "The small-molecule 4’‐bromo‐resveratrol (4’‐BR) has an inhibitory effect on SIRT3, and the reduced expression of SIRT3 could cause metabolism reprogramming, resulting in a significant anti-cancer effect in melanoma cells." (PMID 35832551, 2022). "Our data suggest the melanoma promoting potential of SIRT3 may be linked with alteration in the metabolic phenotypes, and thus SIRT3 inhibition may be a potential strategy to inhibit melanoma progression." (PMID 33937086, 2021). "Remarkably, hypoxia enhances expression of Arg-II in melanoma cells with concomitant suppression of Sirt3 and augmented mtROS along with more deformed nuclei and DNA damage." (PMID 40177131, 2025). "In parallel, silencing of Sirt3 in the melanoma cells resulted in a significant nuclear deformation, an increase in migration and DNA damage." (PMID 40177131, 2025). "As observed in the other cell types, hypoxia also enhanced Arg-II in wt Me276 melanoma cells, which was accompanied by a decrease in Sirt3, increase in nuclear deformation and DNA damage." (PMID 40177131, 2025). "Specifically, in melanoma, SIRT3 is upregulated, and knockdown of SIRT3 has led to reduced proliferation." (PMID 34831420, 2021). "Specifically, our data suggest that modulation of SIRT3 affects the growth of melanoma xenografts as well as various tumor growth markers." (PMID 33937086, 2021). "We investigated the tumorigenic behavior of SIRT3 knockdown and overexpression in melanoma cells in Nu/Nu mice." (PMID 33937086, 2021). "The mice were subcutaneously implanted with Hs294T-empty vector pcDNA 3.1(+) (control) and Hs294T-SIRT3-Flag (SIRT3 overexpressing) melanoma cells and tumorigenicity of the cells was followed." (PMID 33937086, 2021). "For this purpose, Nu/Nu nude mice were subcutaneously implanted with shNS-G361 (control) and shSIRT3-G361 (SIRT3 knockdown) melanoma cells followed by assessing tumor development and progression." (PMID 33937086, 2021). "The mitochondrial sirtuin SIRT3 plays key roles in cellular metabolism and energy production, which makes it an obvious target for the management of cancer, including melanoma." (PMID 33937086, 2021). "Collectively, these results suggest that SIRT3 inhibition affects cellular metabolism, to impart an anti-proliferative response against melanoma." (PMID 33937086, 2021). "Next, we performed the upstream analysis of SIRT3-modulated genes and identified alteration in several crucial upstream regulators that are known to affect cancer/melanoma development and progression." (PMID 33937086, 2021).